SHBG (sex hormone binding globulin)
Diseases named in the same sentence as SHBG in open-access papers (continued):
Sharing a sentence is not in itself a finding about the gene and the disease.
Obesity (continued). "Studies have suggested that the altered sex hormone profile may be ascribed to obesity and IR/hyperinsulinemia, which in turn can decrease oestrogen production and increase FAI by directly decreasing SHBG levels." (PMID 29618342, 2018). "Obesity also leads to hyperinsulinemia and increases IGF1 bioactivity, which, in turn, results in the reduced hepatic synthesis of sex hormone binding globulin (SHBG)." (PMID 30380719, 2018). "Serum SHBG was quantified in 291 Caucasian pregnant women (142 with normal weight, 42 with pregestational obesity, 50 with gestational obesity and 57 with pregestational plus gestational obesity) with uncomplicated pregnancies and parturition." (PMID 30321217, 2018). "While SHBG levels are low in obese children and adults, and portend the development of metabolic syndrome and T2DM, our study of healthy babies born to normal women, found no connection between maternal obesity or newborn adiposity and SHBG levels in newborns." (PMID 27462374, 2016). "It is also known that obesity has a negative influence on levels of testosterone and estrogens, as well as SHBG." (PMID 27256193, 2016). "During the first 9 years of follow-up in SWAN, increases in free androgen index (FAI) as well as decreases in SHBG predicted incident obesity status independent of age." (PMID 27417630, 2016). "Although the decrease may partially be attenuated by increasing levels of sex hormone binding globulin (SHBG), obesity has a major independent impact on the decrease in these levels." (PMID 26209521, 2015). "PCOS was associated with significantly higher LH to FSH ratio, total T, FAI, and lower SHBG levels, independent of obesity." (PMID 24694334, 2014). "PCOS was found to be associated with significantly higher LH/FSH, total T, free androgen index (FAI), and lower SHBG levels, independent of obesity(P < .05)." (PMID 24694334, 2014). "Compared with non-PCOS patients, we found that obesity and FAI were both risk factors for PCOS women, while SHBG acted as a protective factor role on the occurrence of Mets and IR in PCOS women." (PMID 25223276, 2014). "PCOS patients with upper body obesity in comparison with patients with lower body obesity had lower SHBG and higher FAI, but not significantly." (PMID 25246891, 2012). "Pubertal boys with obesity also typically have lower total testosterone levels than normal-weight boys at the same stage of pubertal development, which is likely due, at least in part, to the lower levels of SHBG." (PMID 40863113, 2025). "However, obesity is not a cause of pathological hypogonadism, and proportionately reduced testosterone and SHBG concentrations accompanied by normal serum LH and FSH concentrations confirm a eugonadal state, best described as the pseudo-hypogonadism of obesity." (PMID 40052430, 2025). "Similarly, SHBG, A2M and CRP all showed obesity-dependent levels." (PMID 39972214, 2025). "Considering that our study wasconducted in men < 30 kg/m2, the correlations between IRI and SHBG maybe present even in the absence of established obesity." (PMID 40857627, 2025). "Several studies have demonstrated a negative correlation between obesity and the levels of free testosterone, bioavailable testosterone (free and albumin-bound), and total testosterone (free, bioavailable, and bound to sex-hormone-binding globulin [SHBG]), which is maintained in all age groups." (PMID 39123669, 2024). "Thus, as a result of the study, new data were obtained on the risk role of SHBG-reducing SNP rs10454142 PPP1R21 and the role of its absence on the occurrence of the disease in women without obesity." (PMID 38672173, 2024). "Not surprisingly, maternal SHBG concentrations were positively correlated with maternal estradiol and negatively correlated with maternal BMI; it is well known that estradiol increases and obesity decreases the hepatic SHBG production." (PMID 38397936, 2024).
Obesity (continued). "This evidence shows that circulating SHBG levels have a negative correlation with the development of obesity/overweight patients and have a positive correlation in malnutrition patients; therefore, plasma SHBG levels are correlating with the nutritional state of patients." (PMID 34335746, 2021). "Also, measurements of total testosterone include the fraction that is tightly bound to sex hormone-binding globulin (SHBG), which increases with age and might be a bias for men with conditions that affect SHBG like obesity, or type 2 diabetes mellitus." (PMID 35821995, 2021). "Fourth, other parameters, such as sex hormone-binding globulin, could help to further explain the mechanisms between obesity and precocious puberty, but have not been measured in the present study." (PMID 34712203, 2021). "Several potential reasons have been identified including adiposity-induced suppression of sex hormone binding globulin synthesis which led to greater clearance of E2 and a possible negative effect of obesity on granulosa cell function thereby decreasing inhibin B levels." (PMID 27417630, 2016). "Although mechanisms are speculative, it has been hypothesized that adiposity-induced suppression of SHBG synthesis leads to greater clearance of E2 and a possible negative effect of obesity on granulosa cell function, which in turn decreases inhibin B levels." (PMID 27417630, 2016). "This suggests that IR, and perhaps obesity, both of which are strongly negatively correlated with SHBG, rather than androgens, may be the major determinant of postprandial lipids." (PMID 26989412, 2016). "Additionally, we found that SHBG levels were positively correlated with HDL and apoA and negatively correlated with triglycerides, hypercholesterolemia, fasting insulin, fasting glucose, diabetes, glycated hemoglobin, obesity, BMI, waist circumference, and waist‐to‐hip ratio." (PMID 41427029, 2025). "Moreover, obesity might also affect the metabolism of androgens, which are not bound to SHBG, since both production and metabolic clearance rates of DHEA and Δ4-androstenedione (Δ4A) are equally increased." (PMID 36836575, 2023). "Also, girls and boys with obesity have near 70% of circulating SHBG compared with nonobese." (PMID 34335746, 2021). "In addition to alteration in insulin sensitivity that was independent of obesity, these studies have demonstrated more marked hyperandrogenemia, IR and relative hyperglycemia and lower sex hormone binding globulin (SHBG) in the obese compared with lean women with PCOS24." (PMID 28706269, 2017). "Thus lower SHBG levels born to overweight diabetic women, if confirmed, might be due to diabetes rather than obesity." (PMID 27462374, 2016). "However other research has shown that the apparent association between diabetes and low serum total-T, but not free-T, may be confounded by obesity and low SHBG, which is in line with our findings." (PMID 27552539, 2016). "Notably, both WC and BMI were found to have negative correlations with testosterone, SHBG, FAI, and the T/E2 ratio but a positive correlation with estradiol, particularly in individuals with larger WC and higher obesity classes." (PMID 39224565, 2024). "However, those men with higher FT and SHBG levels had a higher IIEF 5 score, highlighting the negative role of aging, obesity, and chronic diseases on erectile function." (PMID 37020191, 2023). "In addition, as shown by Spearman analysis, liver CAP in PCOS patients with obesity had a positive correlation with ALT, AST, TG, TT, FAI, FIns, and HOMA-IR, and a negative correlation with SHBG." (PMID 37720537, 2023). "Women with PCOS present higher androgen and estradiol (E2) concentrations, hyperinsulinemia, and suppressed sex hormone binding globulin (SHBG) concentrations compared with women without PCOS, while women with PCOS and obesity more often present ovarian dysfunction and amenorrhea." (PMID 33562540, 2021).
Obesity (continued). "Thus, it is possible to hypothesize that the lower serum SHBG levels and higher bioavailable testosterone levels observed among patients with NAFLD in previous observational studies might be affected by obesity, independent of NAFLD." (PMID 36800955, 2023).
Hyperinsulinemia (285 papers, 2005 to 2026). An increased concentration of insulin in the blood. "In PCOS, excess androgen islinked to a rise in belly fat, which causes hyperinsulinemia and dyslipidemia.To raise the amounts of circulating bioactive testosterone, hyperinsulinemiadecreases the amount of hepatic sex hormone-binding globulin (SHBG)." (PMID 40372207, 2025). "Hyperinsulinemia directly promotes endometrial cell proliferation and indirectly increases risk by reducing sex hormone-binding globulin (SHBG), which increases the bioavailability of estrogens." (PMID 41002547, 2025). "Studies have shown that food with high GI and GL can cause hyperinsulinemia and a decrease in sex-hormone-binding globulin, which can cause ovarian dysfunction among women." (PMID 38191428, 2024). "IR leads to hyperinsulinemia, which in turn causes excessive androgen secretion and reduced SHBG synthesis, thereby increasing testosterone levels." (PMID 38610028, 2024). "IR and hyperinsulinemia lead to decreased levels of sex hormone-binding globulin (SHBG), which in turn cause an increase in free androgens and adverse metabolic profiles." (PMID 37768523, 2024). "Hyperinsulinemia also can cause reduced production of Sex Hormone Binding Globulin (SHBG) by the liver and, consequently, leads to increased levels of circulating steroid hormones, such as estrogen and androgens." (PMID 38172476, 2024). "In the case of NAFLD, the compromised liver leads to decreased androgen metabolism and increased metabolism of SHBG, which propagate through different pathways and cause HA, hyperinsulinemia, and resultant infertility." (PMID 37108615, 2023). "Hyperinsulinemia directly increases androgen secretion, but also increases the level of serum free testosterone by reducing the production of SHBG, which causes infertility." (PMID 37002532, 2023). "This association’s proposed mechanisms include hyperinsulinemia, increased unbound androgen level, increased estrogens, and lower levels of sex hormone-binding globulin." (PMID 35326592, 2022). "Hyperandrogenemia is also exacerbated by hyperinsulinemia; decreased concentrations of the sex hormone binding globulin (SHBG) cause a large pool of androgens to circulate in a free biologically active form." (PMID 35207512, 2022). "Hyperandrogenemia is further exacerbated by hyperinsulinemia while decreased sex hormone-binding globulin (SHBG) concentrations cause large quantities of androgens to circulate in a free biologically active form." (PMID 35885005, 2022). "Hyperinsulinemia can induce androgen production and decrease the sex hormone binding globulin level, which further causes visceral fat accumulation." (PMID 30643854, 2018). "Although nonobese women exhibit lower insulinemia and IR associated with higher SHBG levels, hyperinsulinemia is still a common finding in this population." (PMID 25763405, 2014). "Since there is an opposite association between SHBG serum levels and insulin, the presence of hyperinsulinemia in these people can inhibit hepatic synthesis of SHBG." (PMID 24639805, 2013). "Adiposity, with its associated hyperinsulinism, suppresses sex hormone-binding globulin (SHBG) synthesis and therewith the levels of circulating total T." (PMID 23606790, 2013). "Expectedly, SHBG levels significantly decreased across quintiles, since IR/portal hyperinsulinemia are associated with decreased liver production and lower levels of this androgen transporter." (PMID 23046637, 2012). "IR and its resulting compensatory hyperinsulinism are linked to hyperandrogenemia in various ways; for instance, they stimulate the pituitary to secrete luteinizing hormone (LH) and decrease hepatic production of sex hormone-binding globulin (SHBG)." (PMID 35619648, 2022). "This decreased male reproductive ability as a result of T2DM could be linked to hyperinsulinemia and its inhibitory effect on normal spermatogenesis or decreasing the production of sex hormone binding globulin (SHBG)." (PMID 32607132, 2020).
Hyperinsulinemia (continued). "Hyperinsulinemia caused by IR leads to hyperandrogenemia through excess production of androgens by Theca cells in ovaries and also reduces the liver synthesis of Sex Hormone-Binding Globulin (SHBG)." (PMID 31980022, 2020). "Hyperinsulinemia may directly be associated with the development of hyperandrogenism, or activation of cytochrome P450c17 enzyme and the reduction of SHBG synthesis." (PMID 29186759, 2017). "Hyperinsulinemia has also been associated with diminished Sex Hormone-Binding Globulin (SHBG) levels, although insulin appears to be unable to directly inhibit shbg expression; instead, this effect depends on hyperglycemia-mediated Hepatocyte Nuclear Factor 4-α downregulation." (PMID 25763406, 2014). "At the same time, hyperinsulinemia could suppress the synthesis of SHBG in liver and cause the increasing of free testosterone (FT)." (PMID 24799941, 2014). "Thus, hyperandrogenemia potentially may modulate the associations between SHBG levels and hyperinsulinemia also in women with PCOS." (PMID 36968815, 2023). "Furthermore, studies have demonstrated that hyperinsulinemia associated with higher BMIs leads to reduced production of Sex Hormone-binding Globulin (SHBG), which normally inhibits the biological activity of sex hormones, amplifying the effects of increased estrogen." (PMID 38256311, 2023). "Hyperinsulinemia is also associated with decreased plasma levels of sex hormone binding globulin, leading to increases in free (unbound) testosterone and estradiol, and the aromatization of excess androgen to estrogen in adipose tissue may also increase estrogen levels." (PMID 15987426, 2005). "Chronic hyperinsulinemia diminishes the production of hepatic SHBG and increases androgen levels via activating CYP17A1 in theca cells through insulin stimulation." (PMID 41596408, 2026). "Hyperinsulinemia promotes ovarian androgen production and simultaneously reduces hepatic SHBG synthesis, leading to higher circulating free testosterone levels." (PMID 40868057, 2025). "The subsequent hyperinsulinemia suppresses sex hormone-binding globulin (SHBG) synthesis, increasing circulating levels of free testosterone." (PMID 41239503, 2025). "In contrast, 2 h insulin levels were inversely correlated with SHBG (r = −0.43, p < 0.01), reflecting the suppressive effect of hyperinsulinemia on SHBG production." (PMID 40868057, 2025). "Chronic hyperinsulinemia downregulates sex hormone‐binding globulin (SHBG), leading to increased bioavailability of estrogen, a well‐known driver of BC, particularly in hormone receptor‐positive subtypes." (PMID 40195579, 2025). "Hyperinsulinemia can lead to a decrease in the levels of sex hormone-binding globulin (SHBG), thereby increasing the bioavailability of sex hormones and stimulating the secretion of androgens in the adrenal glands and ovaries." (PMID 40150457, 2025). "For example, T2D-related hyperinsulinemia increases the concentration of SHBG, depletes the bioavailable estrogen in breast tissue, and reduces the risk of breast cancer." (PMID 40760716, 2025). "Hyperinsulinemia exacerbates the condition by stimulating LH receptors, inhibiting aromatase activity, and lowering sex hormone-binding globulin (SHBG) levels, thereby perpetuating the syndrome’s pathophysiology." (PMID 40807079, 2025). "Hyperinsulinemia diminishes the synthesis of hepatic sex hormone-binding globulin (SHBG), resulting in elevated concentrations of free androgens in the bloodstream, hence perpetuating the hyperandrogenic condition." (PMID 41010046, 2025). "Hyperinsulinemia, in turn, elevates free sex hormone levels by decreasing sex hormone-binding globulin (SHBG) release, which influences osteoblast and osteoclast function." (PMID 40170859, 2025). "Hyperinsulinemia and subsequent insulin receptor dysfunction constitute the core mechanism suppressing hepatic SHBG synthesis and secretion." (PMID 41427050, 2025).
Hyperinsulinemia (continued). "Hyperinsulinemia also decreases circulating sex hormone-binding globulin (SHBG) levels and increases free testosterone concentrations." (PMID 41573199, 2025). "In the pathogenesis of PCOS, hyperandrogenemia is considered to play a role via hyperinsulinemia that is driven by hepatic sex hormone-binding globulin (SHBG) and increased free testosterone levels." (PMID 40105555, 2025). "An indirect effect of hyperinsulinemia on the reduced hepatic synthesis of sex-hormone-binding globulin (SHBG) has also been demonstrated, resulting in elevated levels of steroid sex hormones." (PMID 41304905, 2025). "IR, affecting approximately 70% of patients, leads to compensatory hyperinsulinemia, which stimulates ovarian androgen secretion while suppressing hepatic sex hormone-binding globulin (SHBG) synthesis." (PMID 40951420, 2025). "Hyperinsulinemia further increases androgen production and reduces sex hormone-binding globulin (SHBG) levels, thereby aggravating symptoms." (PMID 40868057, 2025). "Hyperinsulinemia, a compensatory response to IR, stimulates ovarian androgen production while simultaneously reducing hepatic synthesis of sex hormone-binding globulin (SHBG), further increasing the bioavailability of free testosterone and worsening symptoms." (PMID 40868057, 2025). "Second, hyperinsulinemia suppresses hepatic production of sex hormone-binding globulin (SHBG) and IGF-binding proteins, thereby increasing circulating free androgen and IGF-1 levels that further stimulate ovarian androgen synthesis." (PMID 41476920, 2025). "Hyperinsulinemia further exacerbates endometrial hyperplasia by reducing sex hormone-binding globulin (SHBG), thereby increasing bioavailable estrogen." (PMID 41301707, 2025). "As a consequence of hyperinsulinemia, there is an increased secretion of androgens by theca cells, as well as reduced hepatic synthesis of sex hormone-binding globulin (SHBG)." (PMID 40563843, 2025). "Hyperinsulinemia reduces the production of SHBG in the liver, thus leading to increased levels of free testosterone in the blood." (PMID 40564059, 2025). "SHBG secreted by the liver, the main protein that binds testosterone in the serum, is suppressed by hyperinsulinemia." (PMID 38389707, 2024). "Firstly, in patients with PCOS, IR induces hyperinsulinemia, affects follicular membrane cells, synergizes with luteinizing hormone to increase androgen production, and disrupts the synthesis of sex hormone-binding globulin." (PMID 39600947, 2024). "This also correlates to the relation between hyperinsulinemia/metabolic syndrome and decreased levels of SHBG seen in KS males." (PMID 38816662, 2024). "Hyperinsulinemia stimulates ovarian androgen synthesis while inhibiting SHBG production, thereby elevating testosterone levels." (PMID 39791640, 2024). "This correlation provides an opportunity to use serum SHBG values to characterize insulin sensitivity/hyperinsulinemia." (PMID 38337532, 2024). "Hyperinsulinemia exacerbates hyperandrogenism by decreasing sex hormone-binding globulin (SHBG), increasing free testosterone levels, and worsening clinical manifestations such as hirsutism, acne, irregular menstrual cycles, and infertility." (PMID 39599701, 2024). "Hyperinsulinemia can also lead to a reduction in sex hormone-binding globulin (SHBG) production by the liver, leading to low serum SHBG levels." (PMID 39275277, 2024). "Hyperinsulinemia is responsible for the increased secretion of androgens by the ovaries and adrenal glands, along with the reduced synthesis of sex hormone-binding globulin (SHBG), which consequently leads to excess androgens." (PMID 38136107, 2023). "Studies have proven that due to the compromised liver in NAFLD, there is reduced SHBG, hyperinsulinemia, elevated ALT and AST activities, and testosterone, which must be managed to cure PCOS." (PMID 37108615, 2023).